IL1B (interleukin 1 beta)
Diseases named in the same sentence as IL1B in open-access papers (continued):
Sharing a sentence is not in itself a finding about the gene and the disease.
rheumatoid arthritis (continued). "Blockers of IL1RI and IL-1β have been used in the treatment of rheumatoid arthritis, breast cancer, and other diseases, but there is still a lack of research and application in ocular surface inflammatory diseases." (PMID 36768371, 2023). "Increased succinate in the synovial fluid of patients with rheumatoid arthritis induces macrophages to release IL-1β, promoting inflammation." (PMID 37303600, 2023). "IL-1β is a powerful pro-inflammatory cytokine that plays important roles in systemic disorders including inflammatory bowel disease, type 2 diabetes and rheumatoid arthritis, as well as the early response to infection." (PMID 36981614, 2023). "These cytokines are already associated with diseases such as rheumatoid arthritis and psoriasis (TNF), Castleman disease and rheumatoid arthritis (IL-6), and type 2 diabetes, smoldering myeloma, urate crystal arthritis, and osteoarthritis among others (IL-1β)." (PMID 37112929, 2023). "KEGG signaling pathway analysis suggested that IL1B regulated rheumatoid arthritis and glucocorticoids." (PMID 36105284, 2022). "This indicates that L. casei can inhibit the activation of the pentose phosphate pathway, maintain redox balance, and reduce the production of pro-inflammatory factors IL-1β, IL-6, and IL-17, thereby alleviating rheumatoid arthritis in rats." (PMID 36217542, 2022). "Interleukin-1 beta (IL-1β) is abundantly expressed during diseases such as rheumatoid arthritis and osteoarthritis." (PMID 35566735, 2022). "The same protective effect is observed in a murine model of rheumatoid arthritis where a preestablished Schistosoma infection causes a downregulation of the level of anticollagen IgG, IFN-γ, IL-17A, TNF-α, IL-1β, and IL-6 and an upregulation of IL-4." (PMID 35113966, 2022). "Comparison of the expression of RAGE mRNA, TNF-α, and IL-1β in synovial tissue of patients with rheumatoid arthritis and osteoarthritis revealed that the concentration of TNF-α and IL-1β in synovial tissue of the former was higher than that of the latter." (PMID 35956875, 2022). "IL-1β is a proinflammatory cytokine and has emerged as a therapeutic target for several inflammatory diseases, such as rheumatoid arthritis; however, its role in the development of lung cancer, especially KM-LUAD, is not fully understood." (PMID 35471938, 2022). "Overexpression of miR-125b induces the expression of TNF-α, IL-6 and IL-1β in plasma from rheumatoid arthritis patients, showing a strong positive correlation between miR-125b and TNF-α." (PMID 36668754, 2022). "CpGs in this cluster have previously been reported to be related to the inflammatory disease rheumatoid arthritis, and IL1B and leptin are produced by the fat tissue as commented above." (PMID 36411288, 2022). "IL-1β is a mucosal inflammatory cytokine that is a pathogenic contributor of anemia of inflammation in rheumatoid arthritis (RA) patients with lower iron and hemoglobin than in non-RA patients." (PMID 35956371, 2022). "Recombinant IL-1Ra (generic anakinra) is fully active in blocking the IL-1 receptor 1 (IL-1R1), and thus the activities of IL-1α and IL-1β, and is approved for the treatment of rheumatoid arthritis and several other diseases." (PMID 35448559, 2022). "In rheumatoid arthritis (RA), this uptake and the resulting IL-1β release is significantly increased due to increased expression of the receptor." (PMID 36685206, 2022). "In rheumatoid arthritis synovium, IL1β is involved in cartilage degeneration by stimulating fibroblasts and chondrocytes to secrete matrix metalloproteinase (MMF), which in turn exacerbates synovial inflammation and bone destruction." (PMID 35833125, 2022). "In the collagen-induced rheumatoid arthritis model, CD200Fc treatment significantly lowers expression of pro-inflammatory cytokines (IL-1β and TNFα) and lowers disease severity at 10 days post disease induction." (PMID 35359946, 2022).
rheumatoid arthritis (continued). "As previously reported, SNPs in the proinflammatory cytokine genes IL-1β and IFN-γ are associated with susceptibility to rheumatoid arthritis." (PMID 36553455, 2022). "It was shown that serum Cu level in rheumatoid arthritis patients was elevated and the Cu level in RA patients was positively correlated to IL-1β and tumor necrosis factor-α (TNF-α)." (PMID 35070279, 2022). "Accordingly, a previous study showed upregulation of the F11R gene encoding JAM-A in peripheral blood mononuclear cells from patients with rheumatoid arthritis, a condition characterized by high IL1β release." (PMID 36531986, 2022). "Since pro- and anti-inflammatory cytokines play a key role in the pathogenesis and evolution of the inflammatory state of rheumatoid arthritis, three typical markers of rheumatoid arthritis were monitored: IL-1β, IL-6, and TNF-α." (PMID 36421448, 2022). "The invasion of rheumatoid arthritis synovial fibroblasts is related to the stimulation of IL-1β and the inflammatory response of macrophages." (PMID 34349767, 2021). "TNF-α, IL-1β, and IL-6 have been well documented for their role in several inflammatory conditions, including lung inflammation, rheumatoid arthritis, and intestinal bowel diseases (IBD)." (PMID 34940701, 2021). "Our findings demonstrated that SJT strongly alleviated rheumatoid arthritis and reduced the secretion of IL-6, IL-1β, TNF-α of AIA rats." (PMID 34393779, 2021). "An anti-inflammatory effect of Piperine reported in IL-1β stimulated synoviocytes from patients with rheumatoid arthritis and carrageenan and collagen induced arthritic rat models are also attributed to its antioxidant potential." (PMID 34867361, 2021). "Studies have shown that BF can reduce tumor necrosis factor-α (TNF-α)-induced interleukin-1beta (IL-1β), IL-6 and IL-8 production in rheumatoid arthritis fibroblast-like synoviocytes, suggesting an anti-inflammatory role of BF in these cells." (PMID 35011278, 2021). "In parallel, gout and rheumatoid arthritis (RA) are joint inflammatory diseases in which reducing IL-1β overexpression can represent an efficient therapeutic opportunity." (PMID 34066649, 2021). "- Rheumatoid arthritis is characterized by inflammation of the joints In serum and synovial fluid, there is an increase in IL-1β." (PMID 34434197, 2021). "These details are important because the complement system plays a role in the pathogenesis of multiple pro-inflammatory diseases characterized by increased levels of IL-1β, including septic shock and rheumatoid arthritis." (PMID 34650553, 2021). "IL-1β mainly participates in the immune response and tissue repair in response to inflammatory diseases, especially rheumatoid arthritis, and IL-6 has a similar function." (PMID 33732152, 2021). "IL-37 has an anti-inflammatory effect in rheumatoid arthritis, reduces the secretion of IL-1β, IL-6, and TNF-α and MIP-2, and mediates M2 macrophage polarization." (PMID 34842603, 2021). "Previous studies have documented the role of IL-6 and IL-1β deregulation in the pathogenesis of systemic-onset juvenile chronic arthritis, rheumatoid arthritis and psoriasis." (PMID 33743681, 2021). "The increase in levels of inflammatory cytokines such as tumor necrosis factor-alpha (TNF-α), IL-1β, and IL-6, play an essential role in rheumatoid arthritis." (PMID 34899343, 2021). "TLR7 induced IL-1β production in synovial fibroblasts and M1-type macrophage from rheumatoid arthritis patients was also in an IRF5-dependent manner." (PMID 34950033, 2021). "In vivo evidence for metformin anti-inflammatory mode of action was obtained in a mouse model of rheumatoid arthritis where it primarily affected IL-1β." (PMID 35096812, 2021). "On the other hand, in agreement with the current study, paeonol decreased the TLR4/NF-κB/TNF-α/IL-6 inflammatory signaling pathway in lipopolysaccharide-induced acute lung injury and IL-1β-induced human fibroblast-like synoviocyte rheumatoid arthritis." (PMID 32104151, 2020).
rheumatoid arthritis (continued). "Our studies also found that KM exerts an anti-inflammatory effect in inflammatory pain and rheumatoid arthritis by inhibiting IL-1β and TNF-α production." (PMID 33542692, 2020). "IL-1β, a classic proinflammatory mediator, plays a key role in septic shock, rheumatoid arthritis, inflammatory bowel disease, and type II diabetes and is thus a major therapeutic target." (PMID 32802115, 2020). "Blockade of myeloid specific cytokines IL-1β, IL-12, and IL-23 have proven to be efficient therapies in multiple diseases such as Crohn's disease, ulcerative colitis, rheumatoid arthritis, psoriasis, and systemic juvenile idiopathic arthritis." (PMID 33123148, 2020). "Such approved drugs include inhibitors of TNF-α (e.g., etanercept and adalimumab), IL-6 (e.g., tocilizumab), and IL-1β (e.g., canakinumab) signaling for immune diseases such as rheumatoid arthritis and Crohn’s disease." (PMID 33291425, 2020). "In common inflammatory disorders characterized by pain as a predominant symptom, such as rheumatoid arthritis, osteoarthritis and gout, release of cytokines including IL-1β is well-known to contribute to pathology." (PMID 32973552, 2020). "Since IL-1β promotes Th17 differentiation, IL-1β can be related to many Th17-driven diseases, including rheumatoid arthritis, multiple sclerosis, and psoriasis." (PMID 33144845, 2020). "IL-1β enhances osteoclast formation and bone resorption in rheumatoid arthritis, periodontal diseases, and osteoporosis." (PMID 32708317, 2020). "Stigmasterol can decrease the levels of IL-17, TNF-α, and IL-1β in rheumatoid arthritis, can significantly reduce the plantar edema induced by MSU crystals, and can reduce the serum UA levels in hyperuricemia mice by inhibiting liver XOD activity." (PMID 33149752, 2020). "Pro-inflammatory cytokines including IL-6, IL-1β, and TNF-α are secreted from macrophages after LPS treatment, and they are linked to various chronic diseases, including rheumatoid arthritis, type II diabetes, and cancer." (PMID 32238770, 2020). "Platelet derived EVs also carry cytokines, such as IL-1β and inflammasome components in the synovial fluid, as evidenced in patients with rheumatoid arthritis." (PMID 32859053, 2020). "IL-1Ra prevents the inflammation driven by either IL-1α and IL-1β, and is approved to treat rheumatoid arthritis for subcutaneous (s.c.)administration of 100 mg daily, but is widely used off-label." (PMID 32699149, 2020). "CB2 agonist 4Q3C showed an anti-inflammatory effect in rheumatoid arthritis mouse model (reduced bone erosion, inhibited formation of osteoclasts and lowered the level of TNFα, IL-1β, COX-2 and inducible NO synthase)." (PMID 33036283, 2020). "Exposure of human macrophages to IgG-ICs in conjunction with TLR ligands amplifies production of TNF-α, IL-1β, and IL-6, all of which play critical roles in the pathology of diseases such as rheumatoid arthritis (RA)." (PMID 32719679, 2020). "The IL-6 expression by IL-1β stimulated fibroblast-like synoviocytes derived form patients with rheumatoid arthritis was successfully inhibited by piperine treatment." (PMID 33708109, 2020). "Curcumin, another inhibitor of mTOR signaling, was also reported to alleviate rheumatoid arthritis-induced inflammation and synovial hyperplasia by reducing inflammatory mediators like IL-1β, TNF-α, MMP-1, and MMP-3." (PMID 32867828, 2020). "Human osteocyte-enriched cells were cultured with serum of active rheumatoid arthritis patients ex vivo, which increased IL-1β, TNF-α, SOST, and DKK1 gene expression levels." (PMID 32708317, 2020). "Interleukin (IL)-18 and IL-1β are potent pro-inflammatory cytokines that contribute to inflammatory conditions such as rheumatoid arthritis and Alzheimer’s disease." (PMID 33101286, 2020). "Applying the candidate gene approach, SNPs in IL1β (rs1143634) and KCNQ1 (rs2237892) were shown to be associated with comorbidity of rheumatoid arthritis and periodontal disease." (PMID 30890897, 2019).
rheumatoid arthritis (continued). "Plasma IL-1β level, proinflammatory marker, is higher in rheumatoid arthritis patients than in normal controls and TGF-β, anti-inflammatory marker, also increases in chronic obstructive pulmonary disease patients or in multiple sclerosis." (PMID 31791360, 2019). "In human osteocyte-enriched cell cultures, serum from rheumatoid arthritis patients, IL-1β alone, and a combination of IL-1β, TNF-α, and IL-6 all increased SOST expression." (PMID 31139147, 2019). "Canakinumab, a human antibody against interleukin-1-beta (IL-1β), was first targeted against rheumatoid arthritis." (PMID 31545703, 2019). "GABA acts as anti-inflammatory in rheumatoid arthritis, downregulating mechanisms that lead to the production of pro-inflammatory agents such as IL-1β and also in neuroinflammation in general." (PMID 30858801, 2019). "It has been proposed that GABA acts as an anti-inflammatory in rheumatoid arthritis downregulating mechanisms that lead to the production of pro-inflammatory agents such as IL-1β and also in neuroinflammation in general." (PMID 30858801, 2019). "Dendritic cells that are present in the synovial fluid increase the release of TNF, IL-1β, IL-6, and IL-23 and stimulate Th17-cell differentiation, and thus IL-17 production in rheumatoid arthritis joints." (PMID 31295952, 2019). "IL-17A or IL-17 is involved in several chronic diseases, including rheumatoid arthritis (RA), and it upregulates other proinflammatory cytokines, including IL-1β and IL-6." (PMID 31614911, 2019). "We have previously detected elevated inflammatory mediators in cerebrospinal fluid (CSF) of rheumatoid arthritis (RA) patients, where increased interleukin-1beta (IL-1β) levels correlated positively with fatigue." (PMID 30770760, 2019). "In patients with rheumatoid arthritis, active caspase 1 cleaved IL-1β precursors and IL-18 precursors to IL-1β and IL-18 to induce inflammation, respectively." (PMID 31367484, 2019). "Overexpression of both IL-6 and IL-1β is considered to be an important role in the pathophysiology of rheumatoid arthritis." (PMID 30915347, 2019). "In IL-1β-stimulated rheumatoid arthritis fibroblast-like synoviocytes, inhibition of autophagy by 3-methyladenine partly reversed APS-induced decrease of cell viability, increase of cell apoptosis, and repression of proinflammatory cytokines production." (PMID 30999666, 2019). "For example, the transfection of miR-451 mimics decreases the levels of TNF-α, IL-1β, and IL-6 in synovial fibroblasts isolated from rheumatoid arthritis patients." (PMID 31652441, 2019). "In this study, the anti-arthritic effects of JC3 were evaluated in carrageenan/kaolin-induced rat models and in IL-1β-stimulated rheumatoid arthritis fibroblast-like synoviocytes derived from arthritis patients." (PMID 30565030, 2019). "For example, in mice with multiple sclerosis and rheumatoid arthritis, high serum IL-1β levels correlate with the elevated CNS expression of IL-1β, IL-8, and TNF-alpha." (PMID 31774879, 2019). "IL-1β generation is mainly mediated by the NLRP3 inflammasome, and deletion of Nlrp3, caspase-1 and the IL-1 receptor markedly protects against rheumatoid-arthritis-associated inflammation." (PMID 29743895, 2018). "Replicating even this degree of success in the clinic has proved difficult in clinical trials of alternative agents, for example blocking IL-1β, IL-17 and the IL-12/23 family in rheumatoid arthritis – despite their attractiveness as targets." (PMID 29206659, 2018). "IL-1 is also an important mediator of autoimmune diseases as evidenced by the therapeutic efficacy of IL-1Ra or IL-1β specific antibodies for treatment of rheumatoid arthritis and gouty arthritis." (PMID 30042333, 2018). "In rheumatoid arthritis, IL-1β and TNF-α produced by macrophages in the connective tissue stimulate the production of that MMP by articular chondrocytes." (PMID 30648118, 2018).
rheumatoid arthritis (continued). "TNF‐α and IL‐1β promoted YY1 expression in the fibroblast‐like synoviocytes of rheumatoid arthritis patients." (PMID 29928577, 2018). "Multiple proinflammatory cytokines, such as IL-1β, IL-6, TNF-α, and IL-17, cause cartilage damage and bone destruction in aggravation of rheumatoid arthritis." (PMID 29751535, 2018). "Volin found that in the case of rheumatoid arthritis in the synovial fluid with fibroblasts of the synovial tissue stimulated with IL-1b or TNF-α 40- to 50-fold higher R/C than in unstimulated tissue." (PMID 30174768, 2018). "In the case of IL-8, this chemokine participates to the inflammatory process in the early synovitis of rheumatoid arthritis, and similar to IL-1β, the intra-articular administration has been also used to induce acute synovitis in rabbits." (PMID 28377922, 2017). "In brief, IL-1α is expressed locally, whereas IL-1β is expressed at the systemic level and in inflamed sites as synovial fluids in rheumatoid arthritis or gouty arthritis." (PMID 28197099, 2017). "In humans, excessive IL-1β secretion is known to cause disease and several therapeutic strategies are available to target IL-1β in inflammatory conditions such as rheumatoid arthritis, including the IL-1β receptor antagonist (IL-1ra) anakinra." (PMID 28333114, 2017). "Recently, we were able to show that pharmacological activation of Nrf2 inhibits NF-κB activity as well as the secretion of the pro-inflammatory cytokines IL-1β and IL-6 in an in vitro model of rheumatoid arthritis." (PMID 28448946, 2017). "Neutrophils exposed to chronic inflammatory stimulants like TNFα and IL-1β, such as occurs in rheumatoid arthritis, have altered function." (PMID 26928196, 2016). "Recently, our group reported that GV1001 decreased the production of TNF-α, IL-1β, and IL-6 in peripheral blood mononuclear cells from rheumatoid arthritis patients through the suppression of p38 MAPK and NF-κB activation." (PMID 27655706, 2016). "During inflammation, excess levels of cytokines (IL-1β, IL-6, and TNF-α) lead to the damaging of cells and tissues and the activation of macrophages in inflammation-associated diseases (e.g., rheumatoid arthritis and chronic hepatitis)." (PMID 27493450, 2016). "It has been shown that inhibiting IL-1β/IL-1R1 axis by anakinra, a recombinant IL-1R1 antagonist approved to treat rheumatoid arthritis, is sufficient to reverse DN pathology in mouse model." (PMID 27706238, 2016). "An anti-IL-1β monoclonal antibody (canakinumab) is approved for use in autoinflammatory syndromes and recombinant IL-1R antagonist (anakinra) for rheumatoid arthritis, suggesting a potential role for these drugs in other inflammatory conditions." (PMID 26399326, 2015). "It has been determined that the cPLA2-α gene is regulated by p42/p44 MAPK in response to stimulation by TNF-α and IL-1β in tracheal smooth-muscle cells or rheumatoid arthritis fibroblasts." (PMID 26593914, 2015). "Genes showing lower levels of expression in AD included ICAM-1, IL-1B, CCR1, IFIH1, SOCS1, TNFAIP3 and TNFSF13B, which are strongly associated with acute and chronic inflammation and adult rheumatoid arthritis." (PMID 26310571, 2015). "The clinical efficacy of specific cytokine inhibitors in rheumatoid arthritis (RA) reveals the pivotal role of predominantly monocytic cytokines like IL-1β, TNF or IL-6 in the pathogenesis of the disease." (PMID 26251236, 2015). "And some groups identified FSTL1 as a new proinflammatory mediator that contributes to rheumatoid arthritis by promoting the expression of TNFα, IL-1β, IL-6 and IL-8, as well as by enhancing the interferon-γ (IFN-γ) signaling pathway in a mouse model." (PMID 25888873, 2015). "A first step would be to use anakinra, a specific inhibitor of both IL-1α and IL-1β already clinically applied for the treatment of rheumatoid arthritis in humans." (PMID 25756043, 2015).